FOXL2 (forkhead box L2)
Diseases named in the same sentence as FOXL2 in open-access papers (continued):
Sharing a sentence is not in itself a finding about the gene and the disease.
tumor (continued). "Moreover, ACT experiments also demonstrate that transfer of FOXL2-restricted T cells controls tumor progression, indicating a T cell–mediated effect of the vaccine." (PMID 32814714, 2020). "FOXL2 is rarely mutated in other cancers, with mutations occurring in approximately 1% of all cancers profiled by the GENIE/AACR project and less than 5% of any individual tumor type apart from SCSTs." (PMID 32485873, 2020). "Taken as a whole, these data strongly suggest that the acquisition of FOXL2 homozygous genotype is likely to be involved in tumor recurrence, and might be a marker of early recurrence." (PMID 32064045, 2020). "Although immunization with Foxl2-TT plasmid-DNA significantly reduced tumor progression, we hypothesized that the vaccine’s efficacy could be further improved via combination therapy." (PMID 32814714, 2020). "Moreover, we demonstrated that, in preclinical models, ACT was efficacious in controlling tumor progression of established FOXL2-expressing tumors." (PMID 32814714, 2020). "Combination of FoxL2-TT DNA immunization and anti–PD-L1 further suppresses tumor progression." (PMID 32814714, 2020). "The studies that followed have proven that FOXL2 mutation was present in virtually all AGCTs but was negative in other tumor types." (PMID 30186737, 2018). "Since the proportion of FOXL2-positive cells in cancer stroma varied among cases, we then examined semi-quantitatively whether it depends on histological subtypes or tumor locations." (PMID 30304016, 2018). "Therefore, the tumor exhibited both PMS2 and FOXL2 mutations, and PMS2 mutation occurred before FOXl2 mutation." (PMID 28347324, 2017). "C134W mutated FOXL2 has been shown to inhibit the activin and GDF-9 induction of anti-proliferative follistatin, which may lead to increased cell proliferation and tumor formation." (PMID 24416423, 2014). "No other tumour type identified to date has the same FOXL2 mutation and it seems striking that it occurs in the same position of the gene in GCT, yet little is known about its pathogenic mechanism of action." (PMID 23029457, 2012). "We have reviewed in detail other molecular links between FOXL2 and tumor suppression according to the known literature, and proposed that FOXL2 could indeed act as a novel tumor suppressor." (PMID 20098707, 2010). "Interestingly, FOXL2 has been suggested to be a potential tumor suppressor in colorectal cancer (CRC)." (PMID 20098707, 2010). "Among 12 tumours (12/20; 60%) that were sequenced successfully, none harboured FOXL2 mutations." (PMID 41263790, 2025). "Moreover, the C134W/C134W mutation was not present in the primary tumors but appeared in the recurrent tumor (case #11) in pair 3 and in the late recurrent event (case #14) for pair 4 - suggesting that the acquisition of a homozygous FOXL2 genotype was a secondary event in these cases." (PMID 32064045, 2020). "However, FOXL2 may be either an oncogene or tumor-suppressor gene depending on the genetic context in ovarian granulosa cell tumors." (PMID 30360388, 2018). "In addition to miRNA profiling, we also analysed the FOXL2 mutation status of the juvenile-GCT tumours and demonstrated that the majority of the juvenile-GCT tumours (5/6) carried the wildtype FOXL2 allele, a finding that is consistent with the high specificity of FOXL2 mutation for adult-GCTs." (PMID 28736583, 2017). "For instance, the immunoprofiles of most testicular SCSTs show substantial overlap, with purported ‘sex cord markers’ such as WT1, FOXL2 and SOX9 being expressed in tumours with seemingly pure stromal phenotype and vice‐versa." (PMID 41384702, 2026). "Of note, those groups of FOXL2+COL1A1+ cells, besides positivity for COL1A1, had higher expression of αSMA, PDGFRa, and FAP (frame 2) than FOXL2+COL1A1− tumor cells themselves (frame 1)." (PMID 41042551, 2025).
tumor (continued). "Based on tumor microenvironment composition, we defined two AGCT subtypes: AGCT-1 and AGCT-2 with distinct FOXL2+ cell distributions, differences in progesterone receptor expression, and unique transcriptomic profiles." (PMID 41042551, 2025). "The final classification consisted of (i) tumor areas (FOXL2+/COL1A1−, considered pure tumor) and (ii) collagen-rich areas, including FOXL2−/COL1A1+ stroma, FOXL2+/COL1A1+ stroma, and FOXL2+/COL1A1+ fibromatous tumor." (PMID 41042551, 2025). "Most samples had more than 50% of pure tumor area, which was FOXL2+COL1A1− and exhibited a distinguishable border between COL1A1+ and FOXL2+ staining areas." (PMID 41042551, 2025). "Similar to the adult type, tumor cells express sex cord–stromal markers (SF1, inhibin, calretinin, WT1, FOXL2)." (PMID 38136408, 2023). "Tumor nodules in TGFBR1CA; RosamTmG; Amh-Cre mice were also positively stained for FOXL2 and INHA, consistent with the development of TGCTs." (PMID 38067144, 2023). "We also observed that a homozygous FOXL2 genotype and/or the presence of CIN appeared to predict early recurrence and aggressive tumor behavior." (PMID 32064045, 2020). "Therapeutic FoxL2-TT vaccination suppressed tumor progression compared with control vector (4T1, P = 0.0062; BR5, P = 0.0028) in BR5-FOXL2 and 4T1-FOXL2 tumor–bearing mice and improved mouse survival (BR5, P < 0.02; 4T1, P < 0.04)." (PMID 32814714, 2020). "In the 4T1-FOXL2 model, we also studied the phenotypes of both bulk and FOXL2-reactive T cells, and we found that TN concentrate in the periphery (spleen and lymph node [LN]) whereas TEM accumulate within the tumor, mirroring our human T cell data." (PMID 32814714, 2020). "Therefore this finding demonstrates that altering expression levels of wildtype FOXL2 alone is not important for tumour development, but it is the 402C<G mutation itself in FOXL2 that is responsible for altering biological functions to contribute to GCT pathogenesis." (PMID 23029457, 2012). "Thus, FOXL2 might act as a tumor suppressor in a more systematic way than anticipated." (PMID 20098707, 2010). "Future studies could explore whether ER/PR signaling in FOXL2+COL1A1+ cells modulates ECM composition and mechanical properties in AGCTs, potentially influencing tumor recurrence or therapy response." (PMID 41042551, 2025). "The tumor cells were diffusely positive for α-inhibin, SF1, FOXL2, WT1, and Vimentin." (PMID 41584573, 2025). "Specifically, in FOXL2+COL1A1− cells, we examined expression of other AGCT tumor markers such as SF1, calretinin, and inhibinα, whereas in FOXL2+COL1A1+ cells, we also examined expression of stromal markers, including αSMA, vimentin, S100A4, PDGFRa, PDGFRb, and FAP." (PMID 41042551, 2025). "Immunohistochemistry corresponds to typical sex cord-stromal tumour profile (positivity for SF1, calretinin, inhibin, vimentin, often FOXL2; often oestrogen and progesterone receptor expression; and negativity or weak patchy staining for keratin, negativity for EMA, PAX8, and PAX2)." (PMID 36399188, 2023). "FOXL2 is thought to be a major tumor driver in GCT, although the absence of a FOXL2 mutation in a small subset of AGCTs suggests potential alternative mechanisms for AGCT tumorigenesis." (PMID 32455687, 2020). "Immunization with a plasmid-DNA vaccine encoding murine Foxl2-tt confirms immunogenicity of FOXL2 and controls tumor growth of FoxL2-expressing tumors without affecting female reproductive organs." (PMID 32814714, 2020). "Combination of anti–PD-L1 with FoxL2-TT vaccination further reduced tumor progression and improved mouse survival without affecting the female reproductive system and pregnancy." (PMID 32814714, 2020).
tumor (continued). "In addition, the physical interaction between endogenous FOXL2 and XRCC5 was also observed in various non-tumour cell lines." (PMID 32332759, 2020). "Although UTROSCT demonstrates FOXL2 protein positivity, FOXL2 and DICER1 mutations are not identified in this tumor." (PMID 31739799, 2019). "In one of these four cases, very few FOXL2-positive cells were present close to psammoma bodies (a trace of past tumor tissue) but not around viable tumor cells." (PMID 30304016, 2018). "In contrast to stromal cells, tumor cells did not express FOXL2 except for five cases (5.4%) in which some tumor cells had FOXL2 staining, which was thought to represent aberrant expression." (PMID 30304016, 2018). "Background inflammation, but not histological subtype or origin of the neoplasm seemed to correlate with the proportion of FOXL2-positive cells." (PMID 30304016, 2018). "The presence of plasma cells distant from neoplasm, but not the histological subtype correlated with the proportion of FOXL2-positive cells." (PMID 30304016, 2018). "Moreover, tumors from TGFBR1-CACcre ovaries were highly proliferative, expressed granulosa cell markers FOXL2 and INHA, and were immunoreactive for KRT8 during tumor progression." (PMID 27344183, 2016). "CIMP status was predicted using an established array-based marker panel of CIMP, including B3GAT2, FOXL2, KCNK13, RAB31, and SLIT1, that was shown to identify CIMP+ (CIMP-H or CIMP-L) tumours with 100% sensitivity and 95.5% specificity, with 2.4% misclassification." (PMID 27846243, 2016). "Indeed, the FOXL2 locus was found to be hypermethylated in CRC cell lines and primary tumor samples with inhibition of its expression, whereas the locus was unmethylated in healthy tissue." (PMID 20098707, 2010). "Using a plasmid-DNA vaccine encoding an irrelevant antigen (TEM1) not expressed by 4T1 cells, we proved that solely T cells primed by the FoxL2-TT vaccination, and not by irrelevant antigenic portions of the vector, actively recognize the FOXL2-expressing tumor." (PMID 32814714, 2020). "To determine if FoxL2-TT immune response was T cell mediated and to assess whether adoptive transfer of FOXL2-specific T cells would be efficacious in controlling growth of establish tumors, we performed ACT of T cells from immunized mice to recipient tumor–bearing mice." (PMID 32814714, 2020). "Immunohistochemically, the tumor cells were positive for epithelial markers (AE1/AE3, EMA), a smooth muscle marker (desmin), and less specific sex-cord markers (CD56, WT-1, CD99), but negative for relatively specific sex-cord markers (α-inhibin, calretinin, FOXL2, and SF1)." (PMID 32921307, 2020). "However, for this study, we classified all collagen-rich areas as a single histologic category, reasoning that COL1A1+ fibromatous tumors may exhibit behavior more similar to stromal areas with FOXL2+ cells of any kind than to pure tumor regions without collagen." (PMID 41042551, 2025). "Tumor cells diffusely and intensely express WT1, FOXL2, and SF1, but are usually negative for EMA, AE1/AE3, inhibin, and calretinin." (PMID 38136408, 2023). "Tumor cells are usually positive for calretinin, SF1, smooth-muscle actin, and may express FOXL2, inhibin, and focally AE1/AE3, ER/PR, without nuclear expression of β-catenin or CyclinD1 positivity." (PMID 38136408, 2023). "However, in the present study, due to the big overlap of FOXL2 and COL1A1 staining, we could not make a clear separation between tumor and stromal areas." (PMID 41042551, 2025).
cancer (32 papers, 2009 to 2025). A tumor composed of atypical neoplastic, often pleomorphic cells that invade other tissues. "The functional significance of FOXL2 mutations in other cancers is outside the scope of this review." (PMID 32485873, 2020). "In this patient, KRAS was the only additional cancer gene besides FOXL2 and TERT that was mutated in all samples." (PMID 32455687, 2020). "Our further research indicated that the altered apoptosis and growth of cancer cells might be caused by the related genes that are downstream and regulated by FOXL2, especially tumor necrosis factor (TNF)." (PMID 31221094, 2019). "Additional cancer mutations were detected in OV7 (FOXL2 p.C134W) and OV9 (KRAS p.G12V)." (PMID 28852190, 2017). "Thus, it may be possible to adopt similar strategies for overcoming cancer-associated mutations in DICER1 or FOXL2." (PMID 23641362, 2013). "Among these, we identify a number of known cancer genes (i.e., FOXL2, RUNX1T1), transcription factors (i.e., MEIS2), as well as LHX1 and PAX6 (which are also recurrently affected by mutations)." (PMID 33741928, 2021). "We also found a negative correlation between the chronic inflammation of the background ovary and the proportion of FOXL2-positive fibroblasts in the cancer stroma." (PMID 30304016, 2018). "The tissues were immunostained for forkhead box protein L2 (FOXL2), a transcription factor crucial for ovarian development and function, and markers for cancer-associated fibroblasts (CAFs) and inflammatory cells." (PMID 30304016, 2018). "Given that FOXL2 expression has been reported in some breast and cervical cancers, we don’t exclude that, in addition to being a marker and target in GCT, FOXL2 could be a potential target in those malignancies where its expression is elevated." (PMID 32814714, 2020). "We further found that knockdown of STAT3 or FOXL2 could significantly induce cancer cell apoptosis, indicating the importance of these two genes in cancer cell growth and apoptosis." (PMID 31221094, 2019). "On the other hand, considering the crucial roles of STAT3 in various cancers, as a new downstream regulator gene of STAT3, FOXL2 may have an important function in cancer." (PMID 31221094, 2019). "The transcriptome is therefore an attractive subject of research in cancer and other human pathologies, and some of the cancer genes, such as FOXL2 in granulosa-cell tumors and ARID1A in clear cell carcinomas of the ovary, were initially discovered through transcriptome sequencing." (PMID 29267927, 2018). "Its pervasive presence suggests that FOXL2 is the main cancer driver gene." (PMID 25884336, 2015). "In addition, considering that STAT3 is persistently activated in many human cancer tissues and cell lines, if FOXL2 is clearly regulated by STAT3, the question remains of whether the new STAT3-FOXL2 signaling pathway functions cancer progression." (PMID 31221094, 2019). "These genes include known and novel FOXL2 targets (TGFB2, SMARCA4, HSPG2, MKI67, NFKBIA) and are enriched for neoplastic pathways (Proteoglycans in Cancer, Chromatin remodeling, Apoptosis, Tissue Morphogenesis, Tyrosine Kinase Receptors)." (PMID 33639972, 2021). "Mice immunization with FoxL2-TT controlled growth of FOXL2-expressing ovarian (BR5) and breast (4T1) cancers in a T cell–mediated manner." (PMID 32814714, 2020). "Upon UV exposure, interaction of FOXL2 with both XRCC5 and XRCC6 was significantly diminished in KGN cells, and this effect was consistently observed in other types of cancer cells." (PMID 32332759, 2020).
cancer (continued). "In contrast, the genes FOXL2 and HOXD9 were significantly downregulated in small putative cancer stem cells in comparison to “healthy” small stem cells; their expression was quite comparable to hESCs but not to fibroblasts." (PMID 27703207, 2016). "In addition to proving that the KGN cell line is a useful model to study A-GCTs, these data show that the c.402C>G mutation in FOXL2 is not commonly found in a wide variety of other cancers and therefore it is likely pathognomonic for A-GCTs and closely related tumors." (PMID 19956657, 2009). "The lack of Foxl2 expression prompted us to overexpress mutated Foxl2C389G in BR5 and 4T1 cancer cell lines using a pCMV6-A-PURO vector." (PMID 32814714, 2020). "In this study, we show that FOXL2 could be regulated by STAT3 in cancer cells and that STAT3 binds to FOXL2 at the 5′- GCCTGATGTTTGTCTTCCCAGTCTGTGGCAA-3′ site using EMSA and ChIP." (PMID 31221094, 2019). "This study presents a new upstream regulator of FOXL2 and demonstrats that this new STAT3-FOXL2 pathway has an important function in HeLaHeLa cell apoptosis, providing new insights regarding the targeting of FOXL2 for cancer prevention and treatment." (PMID 31221094, 2019). "Ovarian granulosa cells also express FOXL2, but they can be excluded as a source of CAFs because they are structurally separated from cancer cells by follicular basement membranes and the number of granulosa cells decrease dramatically with age by follicular atresia." (PMID 30304016, 2018). "Further, we found six genes—FOXL2, TNFAIP3, CHD1L, HRAS, KIT, CTCF—that occurred in 12 cases that are not on the top 20 list of any of the four common cancers used for comparison." (PMID 32570879, 2020).
infection (2 papers, 2019 to 2022). The state of being infected such as from the introduction of a foreign agent such as serum, vaccine, antigenic substance or organism. "After 2 h of infection, the transcriptional upstream regulators EGFR, EGR1, FOXL2, FOXO3, IL1A, IL1B and RELA were activated in MKN-28 cells infected with either H. pylori wt or the ΔhtrA mutant, while WWTR1 was inhibited." (PMID 37193047, 2022).
autosomal dominant disease (1 paper, 2012). Autosomal dominant form of disease. "BPES is essentially an autosomal dominant disease, due to mutations in the forkhead box L2 (FOXL2) gene, encoding a forkhead transcription factor." (PMID 22312189, 2012).
hematological malignancies (1 paper, 2022). "Transcription factors activated in both liver and muscle include Irf8, Jun, Egr1, Cebpa, Foxl2, the hypoxia-inducible factor Hif1a, and Runx1, a key regulator in hematological malignancies." (PMID 35865523, 2022).
FOXL2 also shares sentences with these, for which no sentence is quoted: ptosis (34 papers); Epicanthus inversus (5); genetic disorder (4); Azoospermia (2); disease of the lung (2); galactosemia (2); hyperandrogenism (2); Intellectual disability (2); melanoma (2); sex cord-stromal tumor (2); small cell carcinoma of the ovary (2); Addison's disease (1); adenocarcinoma (1); alopecia (1); Alpha-thalassemia (1); amenorrhea (1); autoimmune polyglandular syndrome (1); autoimmune thyroiditis (1); Bamforth-Lazarus syndrome (1); cardiovascular diseases (1); congenital cataracts (1); COVID-19 (1); endometrial stromal tumor (1); Epicanthus (1); epithelial neoplasm (1); epithelial ovarian tumors (1); familial candidiasis (1); fragile X syndrome (1); gastrointestinal stromal tumor (1); hemoglobinopathies (1).
A further 38 diseases each share a sentence with FOXL2 in 1 paper.